IGFBP3 (insulin like growth factor binding protein 3)
Diseases named in the same sentence as IGFBP3 in open-access papers (continued):
Sharing a sentence is not in itself a finding about the gene and the disease.
prostate carcinoma (continued). "Also, the potential role of IGF1, along with IGFBP3, as prognostic markers that can predict mortality in men with advanced prostate cancer, was reported in a recent clinical study." (PMID 24237932, 2013). "Moreover, the addition of recombinant IGFBP3 results in the massive induction of apoptosis, as shown in colon and prostate cancer." (PMID 22401581, 2012). "However, in LNCaP human prostate carcinoma cells 1,25(OH)2D mediated accumulation of p21 mRNA appears to be indirect through induction of IGF binding protein 3 (IGFBP-3) gene expression and suppression of IGF-1 signaling." (PMID 20070897, 2010). "The methylation pattern of IGFBP3 was examined in a panel of prostate cancer cell lines." (PMID 17453001, 2007). "To address whether IGFBP3 methylation is involved in the early stages of disease initiation, we examined the relationship between methylation of IGFBP3 in prostate cancer and HGPIN isolated from the same prostatectomy samples." (PMID 17453001, 2007). "Whether methylation spreading throughout the island in approximately 20% of prostate cancers correlates with a reduction in IGFBP3 expression, warrants further investigation." (PMID 17453001, 2007). "Overexpression of IGFBP3 has dramatic growth-inhibitory and proapoptotic effects in murine prostate tumours and prostate cancer cell lines, indicating that IGFBP3 may act as a tumour suppressor in prostate cells." (PMID 17453001, 2007). "In addition, pharmacological demethylation induced strong expression of IGFBP3 in LNCaP prostate cancer cells." (PMID 17453001, 2007). "Rising PSA levels during the course of prostate cancer progression may facilitate tumorigenesis by digesting IGFBP3 and releasing free IGF-1 into the prostate microenvironment." (PMID 17453001, 2007). "IGFBP3 has been detected in the nuclei of human lung, breast and prostate cancer cells." (PMID 17049074, 2006). "LNCaP prostate cancer cells are similarly growth-stimulated by IGFBP-3 independently of IGFs." (PMID 15642160, 2005). "Two such proteins, RXR-alpha and IGFBP-3, which may be located in a common pathway, have been identified as dysregulated in human prostate cancers." (PMID 15318950, 2004). "Furthermore, experimental pieces of evidence suggested that IGFBP-3 might contribute to the growth and progression of prostate cancer cells." (PMID 35237523, 2022). "However, epidemiological evidence on IGFBP3’s relationship with prostate cancer is mixed." (PMID 28646365, 2017). "However, other studies have failed to confirm the predictive value of circulating IGFBP-3 for increased risk of prostate cancer." (PMID 26217584, 2015). "In a study investigating the effect of dietary intervention, the newly-diagnosed obese prostate cancer patients were randomized to a CR diet group or a control group and differences in weight loss and insulin-like growth factor (IGF)-binding proterin-3 (IGFBP-3) levels were found in the CR group." (PMID 25502434, 2014). "Some limited in vitro evidence suggests a direct link between the IGF-1/insulin axes and vitamin D. For example, laboratory studies on cultured the human prostate cancer cells the LNCaP human prostate cancer cell line have suggested that 1,25-dihydroxyvitamin D3 might influence IGFBP-3 levels." (PMID 22216097, 2011). "In addition, prostate cancer cell lines were employed to test whether promoter hypermethylation affects IGFBP3 gene expression." (PMID 17453001, 2007). "Hence our data raise the possibility that IGFBP-3 is the positive regulator of quercetin-induced apoptosis and quercetin may have some therapeutic value for prostate cancer." (PMID 16600019, 2006). "IGFBP-3 S167 and S175 were identified as the potential sites of phosphorylation by CK2 with S167A-IGFBP-3 mutant having enhanced apoptotic functions in prostate cancer cells." (PMID 36766747, 2023).
prostate carcinoma (continued). "More recently, an assay that evaluates the methylation of GSTP1, SFRP2, IGFBP3, IGFBP7, APC and PTGS2 genes to specifically identify individuals with a severe probability of developing prostate cancer has been proposed." (PMID 37511475, 2023). "Seven m6A methylation-related genes (ALKBH5, FMR1, IGFBP3, RBM15B, YTHDF1, YTHDF2, and ZC3H13) were identified as cross-talk genes between prostate cancer and PD." (PMID 36133437, 2022). "In a prostate cancer mouse model, it directly attacks the IGF/IGFBP-3 protein and lowers its expression by reducing p-AKT and ERK1/2." (PMID 35807549, 2022). "Altogether, these results indicated that UAP1L1 knockdown inhibited prostate cancer cell proliferation, invasion and migration in vitro, but induced cell apoptosis probably through regulating the expression of CD40L, IGFBP-3 and p21." (PMID 35168617, 2022). "It has also been revealed that HOXC6 can help in preventing apoptosis of prostate cancer cells by repressing the expression of neutral endopeptidase (NEP) and IGFBP-3." (PMID 32745141, 2020). "However, in the current analysis there was an interaction of 25(OH)D and treatment arm among men with higher IGFBP-3, suggesting that 25(OH)D may increase the prostate cancer risk in men with higher levels of IGFBP-3 not receiving finasteride treatment." (PMID 28417914, 2017). "This work evaluates the ability of two genes, IGFBP3 and F3, as analyzed in FFPE core needle biopsy tissue, to provide prognostic information about the expected survival time of a prostate cancer patient when combined with currently used clinical parameters." (PMID 26731648, 2016). "The assessment of IGFBP3 and F3 gene expression levels in FFPE prostate cancer tissue would provide an improved survival prediction for prostate cancer patients at the time of diagnosis." (PMID 26731648, 2016). "Multiple biopsy samples from 43 patients were evaluated using a previously reported gene signature of IGFBP3, F3 and VGLL3 with potential prognostic value in estimating overall survival at diagnosis of prostate cancer." (PMID 25296164, 2014). "As the gene expression levels of IGFBP3 and F3 were independent of histopathological grading in prostate cancer area, the same as in benign area, the gene signature may reflect underlying pathogenetic mechanisms of prostate cancer." (PMID 25296164, 2014). "Microarray analysis has shown that vitamin D3 regulates IGFBP3, which sequesters and modulates levels of IGF-I, in LNCaP human prostate cancer cell lines." (PMID 24084056, 2013). "One candidate, IGFBP3, was selected for investigation, along with glutathione-S-transferase pi (GSTP1), a well-known methylation target in prostate cancer." (PMID 17453001, 2007). "IGFBP3 and RXR ligands have additive effects on apoptosis of human prostate cancer cells both in vitro and in vivo." (PMID 17049074, 2006). "Further to this, ADIPOQ, leptin, IGF1, and IGFBP3 ECM proteins are tested among the potential biomarkers whose levels are changed upon physical activity and eating patterns that improve the body composition of prostate cancer survivors (NCT03971591)." (PMID 38255186, 2023). "IGFBP-3 holds major clinical significance, as its expression is predictive of prostate cancer progression, and these studies provide the first evidence for IGFBP-3 as a target to treat therapeutically resistant prostate cancer." (PMID 34284799, 2021). "Treatment of prostate and renal cancer cells with this new compound downregulates nuclear IGFBP-3, through TGF-β, consequently leading to the phenotypic re-differentiation of prostate cancer cells from EMT to MET and ultimately overcoming therapeutic resistance through lifting anoikis resistance." (PMID 34284799, 2021). "Considering these findings, it was expected that low-dose VD3 treatment could provide an advantage in the treatment of prostate cancer cells through IGFBP-3–dependent and IGFBP-3–independent manner." (PMID 32831047, 2020).
prostate carcinoma (continued). "In-vitro studies have shown IGFBP-3 to inhibit proliferation, adhesion, invasion and metastasis of prostate cancer, independent of IGF-1." (PMID 32056047, 2020). "In addition, IGFBP-3 has been shown to suppress tumor-induced NF-κB activity via activation of caspase-8 and caspase-3/7 in an IGF/IGF-IR-dependent manner in prostate cancer cells." (PMID 32443727, 2020). "IGFBP-3 has well-documented roles in the nucleus, and nuclear IGFBP-3 has been reported as a strongly negative prognostic indicator in prostate cancer." (PMID 28778177, 2017). "In the case of human prostate cancer cell lines (PC3 and LNCaP), 24‐hrs treatment with IGF1 and insulin reduced (or tended to reduce) the expression of IGF1R, INSR and GHR, whereas only insulin increased the expression levels of Igfbp3 in LNCaP cells." (PMID 28244645, 2017). "The IGF-I:IGFBP-3 molar ratio, an indicator of bioavailable IGF-I, was consequently lower in patients; 30 % of men with prostate cancer were classified as having high-grade disease (Gleason score ≥7), and 12 % as having locally advanced disease (TNM stages T3-T4)." (PMID 27044414, 2016). "A previously reported expression signature of three genes (IGFBP3, F3 and VGLL3) was shown to have potential prognostic value in estimating overall and cancer-specific survivals at diagnosis of prostate cancer in a pilot cohort study using freshly frozen Fine Needle Aspiration (FNA) samples." (PMID 26731648, 2016). "It was further observed that the mean Ct values of IGFBP3, F3 and VGLL3 of all 97 cancer sample measurements were 28.7, 28.3 and 33.2 respectively, meaning that VGLL3 generally had lower expression levels compared to IGFBP3 and F3 in prostate cancer samples." (PMID 25296164, 2014). "A recent report from our laboratory showed that a gene expression signature of IGFBP3, F3 and VGLL3 could estimate prostate cancer patients' overall survival at the time of diagnosis." (PMID 25296164, 2014). "The assessment of IGFBP3 and F3 gene expression levels in prostate cancer tissue is independent of Gleason patterns, meaning that the impact of operator's choice of biopsy is low." (PMID 25296164, 2014). "This led to the selection of the IGFBP3 gene, whose methylation status has not been previously reported on in prostate cancer." (PMID 17453001, 2007). "These genes, IGFBP3 and RXR-alpha were both up-regulated with respect to Selenium and could be used to suggest a model for Selenium action in prostate cancer." (PMID 15318950, 2004). "In a 6-month study of prostate cancer patients with aerobic or resistance exercise programs, a significant increase in serum IGFBP-3 levels (12.1%; P ≤ 0.05) was observed in the resistance exercise group, while IGFBP-3 levels were reduced by 23.7% (P ≤ 0.05) in the aerobic exercise group." (PMID 36482346, 2022). "In the prostate cancer cells, wild type (wt) IGFBP-3 was equally distributed in the cytoplasmic and nuclear fractions, whereas, mutants of IGFBP-3 at NES, Leu 197 and Leu 200 demonstrated an increased expression of IGFBP-3 in the nuclear fraction in comparison with the wt." (PMID 32478064, 2020). "There was moderate evidence that prostate cancer risk increased with IGF-I (Random effects meta-analysis OR per SD increase in IGF-I 1.09; 95% CI 1.03, 1.16; n = 51 studies) and decreased with IGFBP-3 (OR 0.90; 0.83, 0.98; n = 39 studies), but not with other growth factors." (PMID 28361446, 2017). "In contrast, Battacharyya and colleagues reported that secreted and non-secreted IGFBP-3 may be functionally equivalent in induction of apoptosis in prostate cancer cells." (PMID 23690781, 2013). "However, although it has been described, as an effector of anticancer cancer agents-induced apoptosis, moreover there are no reports available in the role IGFBP-3 in quercetin-induced apoptosisin prostate cancer cells." (PMID 16600019, 2006).
prostate carcinoma (continued). "By contrast, our data indicated that temporal VD3 treatment was enough to sustain prolonged IGFBP-3 expression, suggesting that a temporal higher concentration, rather than a constant concentration, of VD3 may be important in maximizing its efficacy in prostate cancer treatment." (PMID 32831047, 2020). "However, this is balanced by our finding showing that advanced prostate cancer risk was no more associated with IGF-I and IGFBP-3 than prostate cancer risk as a whole; if IGF was associated with progression, it would likely be seen when examining advanced prostate cancer risk." (PMID 28361446, 2017). "In a study about lycopene in prostate cancer treatment, the supplementation did not alter the IGF1 and IGFBP3 levels." (PMID 36501182, 2022). "In ∼700 men without prostate cancer and two replication cohorts (N ∼ 900 and ∼9,000), we examined the properties of these SNPS as instrumental variables (IVs) for IGF‐I, IGF‐II, IGFBP‐2 and IGFBP‐3." (PMID 27225428, 2016). "Our results suggest that IGF-1, IGF-2, and IGFBP-3 measurements have no value in cancer screening, although IGF-1 and IGF-2 may be of aetiological significance in relation to colorectal and prostate cancer." (PMID 16804529, 2006).
lung carcinoma (62 papers, 2002 to 2025). "Elevated plasma levels of IGFBP3 have been associated with lower clinical stage, reduced Ki-67 index, and improved overall survival in lung cancer patients." (PMID 40787454, 2025). "An inverse relationship between plasma or serum levels of IGFBP-3 and lung cancer risk, has been previously reported." (PMID 36766747, 2023). "A 2012 meta-analysis examined the data from six nested case-control groups and eight case-control studies totaling 401 case subjects to discern the association between IGF-I and IGFBP-3 levels and the presence of lung cancer." (PMID 35198099, 2022). "An inverse relationship between plasma or serum levels of IGFBP‐3 and lung cancer risk has been previously shown." (PMID 32592613, 2020). "Lower expression of IGFBP‐3 in lung cancer is known to be associated with poor diagnosis in patients with stage I non‐small‐cell lung cancer (NSCLC)." (PMID 32592613, 2020). "According to early epidemiological studies, low levels of IGFBP-3 were independently associated with a high risk of human malignancies, such as colorectal cancer, lung cancer, and breast cancer." (PMID 26370590, 2015). "Cancer mortality analysis of risk factors associated with all-cause and lung cancer mortality with integration of insulin like growth factor 1 and IGF binding protein 3 (IGFBP3)." (PMID 23405181, 2013). "Epidemiological studies have shown that high IGF-1 and low IGFBP-3 levels are independently associated with a high risk of common cancers, including lung cancer." (PMID 24339922, 2013). "Subsequently, we analyzed the joint effect of cumulative smoking dose with IGF1, IGF2, and IGFBP3 genotypes on lung cancer risk after adjusting for the effect of green tea consumption, exposure to cooking fumes, and family history of lung cancer." (PMID 22347413, 2012). "Concerning the relationship of circulating IGFBP-3 concentration and lung cancer risk, the pooled OR 0.960 (95%CI:[0.591,1.559], P = 0.868) as well as to SMD −0.097 (95%CI:[ −0.264,0.071], P = 0.258) were calculated similar to that of IGF-1." (PMID 23185474, 2012). "As lung cancer is one of the most malignant cancers, we conducted a meta-analysis in order to investigate the strength of association between circulating IGF-1 and IGFBP-3 levels and lung cancer." (PMID 23185474, 2012). "Pooled measure was calculated as the inverse variance-weighted mean of the natural logarithm of multivariate adjusted OR with 95% CIs for highest vs. lowest levels to assess the association of circulating IGF-1 and IGFBP-3 concentrations and lung cancer." (PMID 23185474, 2012). "We also assessed the joint effects of smoking and green tea consumption, and smoking and IGFs and IGFBP3 genotypes on lung cancer risk." (PMID 22347413, 2012). "With precise statistical methods and more studies included in, we got convincing results that the circulating IGFBP-3 level was inversely associated with lung cancer in the case-control studies." (PMID 23185474, 2012). "The joint effect of cumulative smoking dose with IGF1 (CA)n repeat, IGF2 820, IGFBP3 -202 genotypes for lung cancer risk." (PMID 22347413, 2012). "The pooled results of the meta-analysis didn’t show evidence of the relationship between the circulating concentrations of IGF-1 and IGFBP-3 and lung cancer risk in the nested case-control studies." (PMID 23185474, 2012). "As to the relationship between the circulating IGFBP-3 concentration and lung cancer risk, we also calculated the SMD −0.780 (95%CI: [−1.358, −0.201], P = 0.008) with the means and SDs supplied in the articles." (PMID 23185474, 2012). "In this study, we evaluated the effects of smoking, green tea consumption, as well as IGF1, IGF2, and IGFBP3 polymorphisms, on lung cancer risk." (PMID 22347413, 2012). "Here, we evaluated the effects of smoking, green tea consumption, and IGF1, IGF2, and IGFBP3 genotypes on lung cancer risk." (PMID 22347413, 2012).